IL13 (interleukin 13)
Diseases named in the same sentence as IL13 in open-access papers (continued):
Sharing a sentence is not in itself a finding about the gene and the disease.
infection (continued). "By 15 min post-H37Rv infection, a decline of 17 cytokines combined with up-regulation of Ccl24 (26.5-fold), Clec4a2 (23.2-fold) and Pparγ (10.5-fold) indicated an anti-inflammatory response initiated by IL-13." (PMID 22039457, 2011). "Alternative activation of macrophages is induced by IL-4 and IL-13, cytokines that are produced in a Th-2 type response, particularly during allergic, cellular and humoral responses to parasitic and selected pathogen infections." (PMID 20380696, 2010). "However, immunosuppressive cytokines such as IL-10, IL-4 and IL-13 (anti-inflammatory effect) are significantly elevated in the later stage of the infection." (PMID 20169057, 2010). "for example, IL10 helps to control excessive T helper 1 and CD8+ T cell responses that contribute to the immunopathology associated with infection; it also prevents the overproduction of IL4, IL5, and IL13, which can lead to severe fibrosis during the T helper 2 response." (PMID 20398313, 2010). "The earlier and more marked increase in IL-13 expression in the Retnla−/− mice likely explains their enhanced immunity to N. brasiliensis, as IL-13 is the crucial mediator controlling resistance to infection." (PMID 19381262, 2009). "Mice genetically deficient in IL-4, IL-13, or IFN-γ alone or in combination were infected with S. mansoni cercariae and expression of Retnla was measured in the liver by quantitative RT-PCR 9 wk post-infection." (PMID 19381262, 2009). "However, consistent with the ICS results, IL-13 mRNA levels were significantly reduced in the CAT2−/− mice at all time points post-infection." (PMID 18369473, 2008). "Interestingly, increased levels of IL-13 and mucus hyperproduction were observed almost three months after the initial infection with RSV." (PMID 16893457, 2006). "The significance of ILC2s activation during CR infection could lie in production of IL-4 and IL-13 to drive mucus production, in addition to IL-5 which can act synergistically with IL-4 to influence or enhance an antibody response, promoting bacterial clearance." (PMID 40591723, 2025). "Comparative acute-phase profiling of acute CHIKV and DENV infection also found IL-8 (and IL-4) upregulation in both infections, with CHIKV-specific downregulation of IL-13 and MCP-3 and age-associated differences; ex vivo PBMC infection recapitulated the IL-8/IL-13/MCP-3 pattern (but not IL-4)." (PMID 41346606, 2025). "In addition, infection induces the release of IL‐13 into the cavity, which we reason arises at least in part from Th2 cells, since TCR triggering is known to elicit type 2 cytokines from the Th2 cells accumulating in the peritoneal cavity of H. polygyrus‐infected mice." (PMID 41388224, 2025). "However, the polarized type 2 response (IL-4, IL-5, IL-9, and IL-13) might reduce the severity of infection and contribute to the nematode parasite's eradication." (PMID 39103392, 2024). "Thus, by adding IL-13 at concentrations found in mice infected with N. brasiliensis, we hypothesized that we could emulate the effect of innate lymphoid cells during infection and a similar upregulation of goblet cell genes and mucin genes would occur." (PMID 38721267, 2024). "The positive and significant correlations recorded between the amount of CCA with the concentrations of either IL-13 or IFN-γ or IgE indicate that the plasma concentration of IgE as well as those of the two cytokines could be related to the infection intensities inferred from the amount of CCA." (PMID 36889485, 2023). "High infection intensity of S. mansoni should be probably controlled by a major locus SM1 mapped to chromosome 5q31-q33 that contains three cytokine genes notably Interleukin 4 (IL4), Interleukin 13 (IL13) and Interleukin 5 (IL5) that are implicated in the Th2 immune response." (PMID 36889485, 2023).
infection (continued). "Interestingly, application of schistosome eggs, a strong inducer of IL-4 and IL-13 production in vivo, prior to infection of mice with Salmonella typhimurium downregulated the Th17 response in the gut mucosa and impaired the clearance of the bacteria from the gut." (PMID 36753434, 2023). "In line with the modest contribution of Th2/1 cells to IL-4 and IL-13 production and their identification as the main source of parasite-specific IFN-γ production, expanded Th2/1 hybrid cells lead to a further delay in the control of infection in highly susceptible C57BL/6 mice." (PMID 35690651, 2022). "Our data revealed the induction of a heterogenous iNKT cell response during infection which, surprisingly was dominated by the activation of iNKT cells with a mixed type 1/type 2 immune signature and pronounced production of type 2 cytokines, such as IL-13 and IL-4." (PMID 36159876, 2022). "Overall, our results indicate that infections may enhance IL-13/TGFβ1 pathway-mediated fibrosis." (PMID 34858903, 2021). "However, because we observed an association of IL-13 but not IL-4 with severe disease in patients, we hypothesized that IL-13 signaling in the lung following infection was contributing to worse outcomes." (PMID 34185704, 2021). "Thus, in our model, we accessed the bronchoalveolar lavage levels of cytokines associated with different cellular profiles, IL-4 and IL-13 (Th2), INF-γ (Th1) and IL-17 (Th17) of XID and BALB/c mice before infection (day 0) and 7 and 9 days after infected with C. gattii." (PMID 34526536, 2021). "At the same time, downregulation of Th2 cytokines, such as IL4/IL13, as well as IL10 and TGFβ, which are primarily associated with tissue repair and extracellular matrix composition, was observed during the late stage of infection, especially in infected fish at 11°C." (PMID 32695119, 2020). "This factor's crucial role is neatly illustrated in Hymenolepis diminuta infection; STAT-6 knockout mice infected with this tapeworm were unable to clear this infection due, in part, to diminished goblet cell response, unlike their IL-13 and IL-4 deficient counterparts at 12 days post-infection." (PMID 33013869, 2020). "In murine models, infection with helminths led to the reduction of Bacteroidales and the concurrent expansion of Clostridiales communities, which was hypothesized to stimulate an anti-inflammatory response (increased IL-5 and IL-13) in the host." (PMID 32450885, 2020). "While it is known that parasites migrate from the site of infection to the lesion-draining lymph nodes, we were interested to determine if L. major parasites were using CD11b+ Mo-DCs or CD11b+ cDCs to disseminate to peripheral organs, and if IL-4/IL-13 signaling influenced this process." (PMID 32039054, 2019). "Moreover, significant elevations in the levels of plasma Th2 cytokines (IL-4, IL-13, and IL-10) and serum enzymes (alanine aminotransferase and aspartate aminotransferase) reflecting altered liver function were detected in response to the infection." (PMID 30619361, 2018). "Thus, it is tempting to speculate that also during T. muris infections, AREG may contribute to host resistance by licensing activated Th2 cells to express IL-13 at the site of infection in an IL-33-dependent way." (PMID 29045902, 2017). "Therefore, high levels of IL13 may make severe MPP children lose the ability to eradicate MP from the lung in primary infection, resulting in longer lasting MP infection and a hyper-immune response." (PMID 28302172, 2017). "Consequently, the lack of IL-13 expression by CD4+ T cells at the site of infection is likely to be causative for the enhanced susceptibility of Egfrfl/flxCd4-cre mice to H. polygyrus infection." (PMID 29045902, 2017). "Moreover, IL-4 and IL-13, key cytokines associated with M2 macrophages, were not modulated by the infection or the absence of Ebi3 in the hearts of animals." (PMID 29033934, 2017).
infection (continued). "Interestingly, the reconstitution with serglycin-competent bone marrow derived MCs restored the IL-13 levels almost to WT levels, suggesting that serglycin-competent MCs may contribute an important part of the IL-13 secreted during infection." (PMID 27267469, 2016). "Of note, the two previous reports of associations with these functional IL13 polymorphisms included subjects with acute infection, whereas our study group of chronically infected subjects did not include subjects during the acute phase of infection." (PMID 26258681, 2015). "To investigate how IL-33 might interfer with the host immune response, we measured the levels of the key Th1 cytokines (IFN-γ, IL-12 and TNF-α), key Th2 cytokines (IL-4, IL-5 and IL-13), and the regulatory cytokine IL-10 in the serum at various time-points after infection with PbA." (PMID 25659095, 2015). "Levels of IL-33 during infection was influenced by age at the time of initial infection; and this, in turn, correlated with an increase in the numbers of lung ILC2s coinciding with enhanced IL-13 expression and increased lung dysfunction (i.e. AHR) and pathology." (PMID 26473724, 2015). "Moreover, Trichuris infection was associated with increased plasma levels of pro-inflammatory (IL-1β and IL-17α), anti-helminthic (IL-13) and regulatory (IL-10) cytokines, which closely correlated with each other; showing a mixed cytokine response to infection with Trichuris." (PMID 24675895, 2014). "However, MMR and not DC-SIGN expression is associated with HIV-1 trans infection of T cells by IL-13-treated MDM that express both." (PMID 24278768, 2013). "Thus, while susceptible BALB/c mice deficient in the ability to respond to the cytokines IL-4/IL-13 are not protected against development of cutaneous leishmaniasis caused by L. major they are totally resistant to infection with L. mexicana." (PMID 21245915, 2011). "This highlights the role of IL4/IL-13 in driving a non-healing response and may in part explain why human males are more susceptible to this infection than females." (PMID 21245915, 2011). "Therefore, the effects of IL-13 depletion on in vitro infection were assessed after 24 hours." (PMID 21573182, 2011). "Complementation with pBAH001 or pBAH002 partially rescued production of IL-8, IL-13, IFN-γ, IL-1β, and IL-6, with greater cytokine production occurring with ΔflgB (pBAH001) infection compared to ΔflgB (pBAH002)." (PMID 41459941, 2026). "Tuft cells can recognize infections from Nippostrongylus brasiliensis, Trichinella spiralis, and Helicotylenchus, releasing IL-25 to increase ILC2 numbers and subsequently IL-13 secretion, which acts on ISC to differentiate into more tuft and goblet cells." (PMID 40069907, 2025). "As IL-13 has been shown to affect infection outcomes following CDI, we assessed the functional role of ILC2 during early CR infection by injecting anti-IL-13 IP on days 2 and 4 post-infection." (PMID 40591723, 2025). "Nine days post‐infection, there was an increase in the expression of cell‐surface CD154 in CD4+ T cells together with increased IL‐13 levels in the cavity, suggestive of local antigen presentation." (PMID 41388224, 2025). "Infection of PBECs with RVA16 at MOI 1 for 48 h.p.i resulted in the upregulation (> twofold) of IL-1β and IL-13 expression in PBEC donor cells." (PMID 40916026, 2025). "Second, the IL-13-induced secondary inflammatory cluster–enriched for IL-15, TNF-NFκB signaling, ER stress, and cell-death pathways–was most strongly induced at later infection timepoints." (PMID 41427379, 2025). "Monocyte depletion had negligible effect on cytokine production 4 h post infection, with only MIG (CXCL9) and IL-13, significantly altered in the BALF of CCR2-depleted mice compared to WT, out of the 32 quantified secreted factors." (PMID 39418302, 2024).
infection (continued). "Concurrently, the cytokine expression profile demonstrates a gradual elevation in IL5, IL13, IFNγ, and TNF, indicating an increasingly complex immunomodulatory environment according to the infection dose." (PMID 39621794, 2024). "Later after infection (day 10), FITC-dextran levels in baso IL-4/IL-13 (−) mice were negatively correlated with IL-17A, which was the center of a larger network of positively correlated type 1 plasma cytokines." (PMID 38780542, 2024). "In agreement, no cytokines or chemokines were found to be significantly regulated at the transcriptional level and two proteins related to recruitment and activation of immune cells were less abundant post infection compared to controls (CCL26 and IL13)." (PMID 39247193, 2024). "The expression of GM-CSF, IL-4, IL-5, IL-10, IL-13, KC, and VEGF in Th2 cells, and IL-2, IL-4, IL-5, IL-10, and IL-17 in NK cells significantly increased after infection (PBS-treated group)." (PMID 39264964, 2024). "With respect to the female response to infection-induced neuroinflammation, there was significant upregulation in the expression of CXCL9, CXCL10, BDNF, IL-13 and KCNN4 in the medulla oblongata." (PMID 38879567, 2024). "In another study, upregulation of Th1 cytokines [IFN-γ, interleukins (IL)-2 and IL-12p40] and Th2 cytokines (IL-4, IL-5, IL-13 and IL-10) was thought to play a crucial role in driving cellular immune responses against IBDV in the acute phase of infection." (PMID 37744374, 2023). "TNF-α, IL-6, IL-8, IL-10, IL-13, and IL-33 in children with HRSV were significantly increased in severe infection compared to mild infection (p < 0.05) in children with HRSV." (PMID 37239461, 2023). "TNF-α, IL-6, IL-8, IL-10, IL-13, and IL-33 in children with HRSV were significantly increased in severe infections compared to mild infections." (PMID 37239461, 2023). "Within splenocytes, expression of IFNγ, TNFα, IL17, IL13, IL10, and TGFβ were changed by both infection and vaccination within CD4 and CD8 T cells and regulatory T cells." (PMID 36799886, 2023). "High concentrations of IFNɣ, TNFα, IL-10, IL-13, and MIP-1β were found during infection, as well as high concentrations of IL-7 and MCP-1 after recovery, in both the hospital ward and the ICU." (PMID 36975498, 2023). "As depicted in, TNF-α, IL-6, IL-8, IL-10, IL-13, and IL-33 in children with HRSV were significantly increased in severe infection compared to mild infection (p < 0.05)." (PMID 37239461, 2023). "More importantly, both SARS-CoV-2 and pCoV-GD01 infection induced the production of cytokines such as IFN-gamma, IL-12p70, IL-13, IL-2, IL-5, TNF-alpha, IL-17A, IP-10, MCP-3, MIP-1beta, MIP-2, Exotaxin, IL-15/15R, IL-28, IL-3, G-CSF, IL-1alpha and ENA-78." (PMID 37330497, 2023). "In this study, we observed that mice treated with HK-fbp1 at day 3 after infection exhibited high Th1 and Th17 protective responses, evident by increased production of IFN-γ and IL-17A cytokines and reduced Th2 cytokines (IL-13)." (PMID 36719231, 2023). "Prior to infection, an imbalance between Th1, Th2, and Treg cytokines was observed in PFOA-exposed mice, suppressing IL-4 and IL-13 production." (PMID 37600798, 2023). "•Plasmatic concentration of IgE, IL13 and IFNG was correlated with the infection intensities of S. mansoni." (PMID 36889485, 2023). "Protein and mRNA levels of IL-6 and IL-1β were significantly reduced in ASO MIR99AHG treated BMDMs compared to controls following IL-4/IL-13 stimulation and Mtb HN878 infection." (PMID 35895506, 2022). "A more persistent effect on cardiac fibrosis and systolic function at 35 days post-infection required the combined expression of IL9 with IL3, IL4, IL13, and IL15." (PMID 35508525, 2022). "We found cytokines like IFNγ, IL-4, IL-13, IFNβ1, TNFα, and transcriptional regulators such as HIF1α, STAT1, CTCF, TP73, IRF1, MXD1, ATF4, SPI1 mediate macrophage activation upon infection." (PMID 35789215, 2022).
infection (continued). "First of all, compared to the wildtype MYXV infection-triggered response, ΔM062R infection seems to specifically downregulate the immunosuppressive pathways including IL10 and IL4/IL13 pathways, as revealed by both REACTOME and GO analysis." (PMID 36103568, 2022). "We also identified a 73% reduction of MIR99AHG expression at 24 h post IL-4/IL-13 stimulation and a 69% reduction at 4 h post Mtb HN878 infection." (PMID 35895506, 2022). "We previously utilized deep CAGE (Cap Analysis of Gene Expression) transcriptomics to define the transcriptome of M1 (IFN-γ) or M2 (IL-4, IL-13, IL-4/IL-13) activated BMDMs and during Mtb HN878 infection." (PMID 35895506, 2022). "In contrast, Th2 cells producing IL-4, IL-5 and IL-13 are associated with activation of granulocytes involved in allergic reactions as well as activation of B cells and humoral immunity that are usually not effective in intracellular infections such as Mtb nor in anti-tumor responses." (PMID 36591229, 2022). "We show that infection with the intestinal nematode H. polygyrus promote homing to and long-term residence of H. polygyrus-specific TH2 cells producing IL-4 and IL-13 in the skin." (PMID 34931000, 2022). "Infection with O. dentatum significantly increased expression of IL4, IL13, ARG1, CCL17 and CCL26, with a concurrent trend for down-regulation of the expression of Th1-related genes such as IL8." (PMID 35069576, 2021). "Peripheral monocytes, which are recruited to the site of infection, produce TGF-β and differentiate into monocyte-derived CX3CR1+ macrophages, which become alternatively activated due to IL-4/IL-13 signaling via IL-4Rα." (PMID 33829283, 2021). "Compared to RV-A1B, RV-C15 infection induced significantly higher mRNA expression of CXCL1, CXCL2, IL-5 and IL-13." (PMID 33968043, 2021). "Among serum molecules identified in non-neurological and neurological diseases in the acute phase of the infection, 12 (IL-1β, IL-6, TNF, IL-2, IL-7, IL-17A, IL-15, IFN-α, IL-5, IL-13, IL10, and GM-CSF) were shared by both networks." (PMID 33776990, 2021). "The results showed that after infection with YJ016, the plasma levels of IL-2 and IL-23 in the Pair group were higher than those in the EtOH group; IL-13 and IFN-γ were lower in the EtOH group than in the Pair group." (PMID 34489943, 2021). "We observed that infected WT mice exhibit a mixed response of Th1 and Th2 already in the initial stage of infection (3dpi), represented by an increase in IFN- γ, IL-1β, IL-33, IL-13 and IL-5." (PMID 34324507, 2021). "Compared to sham treatment, RV-C15 infection significantly increased mRNA expression of IFN-γ, CXCL10, CXCL1, CXCL2, TNF-α, IL-12, IL-25, IL-13 and IL-5." (PMID 33968043, 2021). "We have previously reported that infection with SARS-CoV-2 in this model results in lung damage; however, IL-13 blockade resulted in little change in lung injury." (PMID 34185704, 2021). "Brain fibrinogen was related to IL-1β (and IL-13 to a smaller extent) in early and intermediate stages of disease (BS0–II and III–IV) but the relationship was lost in end stage disease, or with infection." (PMID 33723589, 2021). "Wild type BALB/c pups had peak levels of IL-13, IL-5 and IL-4 in the BALF at day 27 post infection with P. murina." (PMID 34682248, 2021). "At 7-weeks post-infection the human cytokines IFN-γ, TNF-α, IL-12p40, IL-10 and IL-13 were elevated in humanized mice infected with HTLV-1, S. stercoralis or with the dual infection, as compared to background controls." (PMID 34314415, 2021). "RV-C15 infection induced airway expression of IL-25, IL-33 and TSLP, innate cytokines responsible for activation of IL-5- and IL-13-producing ILC2s expansion." (PMID 33968043, 2021). "Although some studies indicated that IL-4, IL-10, IL-13, and IFN-γ produced by activated T cells in response to infection likely disrupts OC signaling, the RANK-RANKL signaling pathway is central in the differentiation of OCs." (PMID 33735306, 2021).